TRIM16 (tripartite motif containing 16)
Description:
E3 ubiquitin ligase that plays an essential role in the organization of autophagic response and ubiquitination upon lysosomal and phagosomal damages. Plays a role in the stress-induced biogenesis and degradation of protein aggresomes by regulating the p62-KEAP1-NRF2 signaling and particularly by modulating the ubiquitination levels and thus stability of NRF2. Acts as a scaffold protein and facilitates autophagic degradation of protein aggregates by interacting with p62/SQSTM, ATG16L1 and LC3B/MAP1LC3B. In turn, protects the cell against oxidative stress-induced cell death as a consequence of endomembrane damage.
Synonyms: EBBP
Tractability: Antibody: its Gene Ontology location is reachable by antibodies, with high confidence. PROTAC: UniProt records ubiquitination sites on it; ubiquitination databases record sites on it.
Gene: Protein-coding gene on chromosome 17 (15,627,950 to 15,684,311, reverse strand). Ensembl gene ENSG00000221926.
Subcellular location: Cytoplasm
Subcellular location (Human Protein Atlas): Cytosol; Plasma membrane
Gene Ontology:
Molecular function: DNA binding; interleukin-1 binding; NACHT domain binding; protein binding; ubiquitin protein ligase activity; zinc ion binding
Biological process: positive regulation of DNA-templated transcription; positive regulation of interleukin-1 beta production; positive regulation of keratinocyte differentiation; positive regulation of retinoic acid receptor signaling pathway; response to growth hormone; response to retinoic acid
Cellular component: cytoplasm; cytosol; PML body
Genetic constraint (gnomAD): Loss-of-function variants: 33 observed, 48.69 expected, observed/expected ratio (o/e) 0.68, 90% interval 0.51 to 0.91. The upper end of that interval is the gene's LOEUF score, 0.91, which puts it in group 3 of 6, group 1 being the genes least tolerant of losing a copy. Missense variants: 572 observed, 679.78 expected, observed/expected ratio (o/e) 0.84, 90% interval 0.79 to 0.9. Synonymous variants: 218 observed, 267.63 expected, observed/expected ratio (o/e) 0.81, 90% interval 0.73 to 0.91.
Homologues: Orthologues: chimpanzee TRIM16 (99% identical), chimpanzee TRIM16 (98% identical), macaque TRIM16 (95% identical), rabbit TRIM16 (79% identical), dog TRIM16 (79% identical), guinea pig TRIM16 (78% identical), mouse Trim16 (77% identical), pig TRIM16 (75% identical), tropical clawed frog trim16 (47% identical), zebrafish trim16 (42% identical). Paralogues in human: TRIM25 (18% identical), TRIM39 (16% identical), TRIM11 (16% identical), MEFV (16% identical), MID1 (16% identical), MID2 (16% identical), TRIM41 (16% identical), TRIM14 (15% identical), TRIM47 (15% identical), TRIM27 (15% identical), BSPRY (14% identical), TRIM21 (14% identical), and 68 more.
Diseases named in the same sentence as TRIM16 in open-access papers:
TRIM16 is named in the same sentence as 57 diseases in open-access papers, as found by Europe PMC text mining. Sharing a sentence is not in itself a finding about the gene and the disease. The quoted sentences say what the papers report.
melanoma (10 papers, 2014 to 2024). A malignant, usually aggressive tumor composed of atypical, neoplastic melanocytes. "We have also shown that high TRIM16 protein expression is associated with favourable outcome in melanoma patients with stage III disease." (PMID 33184347, 2020). "Next, we assessed the impact of keratinocyte TRIM16 loss on the development of melanoma in the skin after carcinogen treatment." (PMID 31342168, 2019). "This study provides the first evidence that keratinocyte loss of the putative melanoma tumour suppressor protein, TRIM16, enhances melanomagenesis." (PMID 31342168, 2019). "We used human melanoma cell lines and excised human melanoma samples to show that loss of TRIM16 expression led to enhanced cell migration in vitro, and metastatic disease in vivo." (PMID 25333256, 2014). "Lastly, low TRIM16 expression associated with poor prognosis in melanoma patients with lymph node metastasis, collectively indicating that TRIM16 represents a novel therapeutic target in melanoma." (PMID 25333256, 2014). "We found an E121D missense mutation in exon 1 of IPC-298, in the B-Box1 domain of the TRIM16 protein in 1/9 melanoma cell lines." (PMID 25333256, 2014). "Conversely, transient overexpression of TRIM16 for 48 hours in G361 melanoma cells caused a reduction in cell migration into a scratch wound in vitro over an 8 hour period (P<0.001)." (PMID 25333256, 2014). "Moreover, BRAF inhibitor treatment increased the TRIM16 production in melanoma cells, while TRIM16-deficient mice exhibited elevated incidence of metastasis compared to the control animals." (PMID 33430277, 2021). "We hypothesize that keratinocyte loss of TRIM16 can increase melanoma cell migration and metastasis due to reduced paracrine expression of IFNβ1." (PMID 31342168, 2019). "As melanoma skin lesion size is an important prognostic indicator clinically, we compared the lesion size for the different genotypes to determine if there was a correlation with loss of keratinocyte TRIM16 expression." (PMID 31342168, 2019). "The overexpression of TRIM16 in melanoma cell lines resulted in reduced cell proliferation and migration." (PMID 34639015, 2021). "TRIM16 protein is increased with vemurafenib treatment and is required for the drug action in melanoma cells." (PMID 34639015, 2021). "It was reported that the TRIM16 level in melanoma was lower compared to the normal melanocytes, which also correlated with a rate of lymph node metastasis in TRIM16LOW melanoma patients." (PMID 33430277, 2021). "The WFA therapy was found to induce TRIM16 mRNA expression in melanoma cell lines, while TRIM16 was expected to trigger the highest cytotoxic action." (PMID 33919088, 2021). "We found that in line with our cell viability data, WFA induced necrosis in WFA treated melanoma cells, however, knockdown of TRIM16 rescued the cells from the cytotoxic effects induced by WFA." (PMID 33184347, 2020). "We identified that repression of the tumour suppressor TRIM16 diminished WFA cytotoxicity, suggesting that TRIM16 was in part responsible for the cytotoxic effects of WFA in melanoma cells." (PMID 33184347, 2020). "Together our data indicates that WFA has potent cytopathic effects on melanoma cells through TRIM16, suggesting a potential therapeutic application of WFA in the disease." (PMID 33184347, 2020). "Here, we have shown that WFA treatment induced TRIM16 mRNA expression in melanoma cell lines and that TRIM16 was required to induce maximal cytotoxic effect." (PMID 33184347, 2020). "We found that wild-type TRIM16+/+ mice developed smaller melanoma lesions with skin carcinogen treatment (**P = 0.0073) compared to either TRIM16 keratinocyte knockout genotype mice." (PMID 31342168, 2019). "We noted an increase in the number of melanomas in the heterozygous KRT14-Cre/TRIM16+/flox mice, compared to other genotypes, at 15 weeks (*P = 0.0129)." (PMID 31342168, 2019).
melanoma (continued). "Further investigation is required to determine if TRIM16 is a tumour suppressor protein in melanoma and this requires developing a melanocyte-specific TRIM16 knockout mouse model that ascertains the function of TRIM16 in contributing to melanomagenesis." (PMID 31342168, 2019). "As melanoma is a highly metastatic tumour type, we investigated the potential role of suppression of TRIM16 expression in metastasis of melanocytic lesions to the surrounding lymph nodes." (PMID 31342168, 2019). "Our data also suggest that TRIM16 expression in keratinocytes is involved in cross talk between keratinocytes and melanocytes, and has a role in melanoma tumorigenesis." (PMID 31342168, 2019). "In conclusion, this study suggests that keratinocytes influence melanoma development and provides the first insight into how keratinocyte TRIM16 expression impacts melanoma development." (PMID 31342168, 2019). "Here, we show that TRIM16 expression induced apoptosis in a range of melanoma cell lines and that the specific expression of TRIM16 with combination treatment was required to induce maximal cytotoxic effect." (PMID 27447557, 2016). "We have shown previously that high TRIM16 expression correlates with favourable patient prognosis in a cohort of stage III melanoma patients." (PMID 27447557, 2016). "In melanoma cells, loss of TRIM16 expression is a marker of cell migration and metastasis, while the BRAF inhibitor, vemurafenib, induces melanoma cell growth arrest in a TRIM16-dependent manner." (PMID 27447557, 2016). "We performed immunoblotting to assess TRIM16 protein expression following C012, vemurafenib or C012 and vemurafenib combination treatment of melanoma cell lines." (PMID 27447557, 2016). "We have previously shown that TRIM16 is significantly decreased during melanoma tumorigenesis and is a candidate tumor suppressor in metastatic melanoma." (PMID 27447557, 2016). "The combination of C012 with vemurafenib decreased melanoma cell viability, and increased TRIM16 protein expression in vitro and in vivo." (PMID 27447557, 2016). "After 72 hours of vemurafenib treatment at doses of 0–0.5 μM in A375 and Mel-CV melanoma cells, TRIM16 protein expression increased in a dose-dependent manner." (PMID 25333256, 2014). "We next assessed the effects of vemurafenib treatment on TRIM16 protein stability using cycloheximide (CHX) chase studies, and found that vemurafenib markedly increased TRIM16 protein stability in melanoma cells." (PMID 25333256, 2014). "Here we define an important role for TRIM16 expression in the early stages of melanomagenesis as an inhibitor of cell growth and migration through its effects on the melanoma cell expression of the inflammatory cytokine, IFNβ1." (PMID 25333256, 2014). "We propose that TRIM16 suppresses melanoma cell growth via the upregulation of c-Jun and the formation of the enhanceosome promoter complex that is required for IFNβ1 gene transactivation." (PMID 25333256, 2014). "The TRIM16 protein half-life in melanoma cell lines, A375 and Mel-CV, was 12 hours and 6 hours, respectively, compared with more than 24 hours in NHEM and normal human fibroblasts (WI38)." (PMID 25333256, 2014). "Overexpression of TRIM16 in melanoma cells up-regulated IFNβ1 and c-Jun levels, which was required for the anti-proliferative TRIM16 effect." (PMID 25333256, 2014). "To evaluate the possible therapeutic application of TRIM16 expression patterns on the treatment of melanoma, we investigated the effect of the BRAF inhibitor, vemurafenib, on TRIM16 expression levels." (PMID 25333256, 2014). "To determine the effects of TRIM16 overexpression on melanoma cell growth, we transiently transfected 5 melanoma cell lines with the pcDNA3.1 empty vector or pcDNA3.1/TRIM16/myc.his expression vector." (PMID 25333256, 2014). "The BRAF inhibitor, vemurafenib, increased TRIM16 protein levels in melanoma cells in vitro, and induced growth arrest in BRAF-mutant melanoma cells in a TRIM16-dependent manner." (PMID 25333256, 2014).
melanoma (continued). "TRIM16 knockdown strongly increased cell migration in normal human epidermal melanocytes, while TRIM16 overexpression reduced cell migration and proliferation of melanoma cells in an interferon beta 1 (IFNβ1)-dependent manner." (PMID 25333256, 2014). "To investigate potential downstream target genes of TRIM16 in melanoma, we performed a Cancer Pathway PCR Array using mRNAs from G361 cells transiently transfected with empty vector or TRIM16 expression vector for 48 hours." (PMID 25333256, 2014). "We showed that TRIM16 protein expression by IHC was significantly increased in patient melanoma tissues during early treatment with BRAF inhibitors (p=0.0018, two sided t-test, 95% confidence intervals 0.4 to 1.3) and reduced at relapse." (PMID 25333256, 2014). "We next performed DNA sequencing of the endogenous TRIM16 coding and promoter regions for 9 melanoma cell lines." (PMID 25333256, 2014). "TRIM16 protein levels were significantly increased in the four melanoma cell lines following 5-Aza treatment (P=0.018 for Mel-JD, P=0.025 for Mel-RM, P=0.011 for A375 and P=0.0001 for Mel-CV), compared with normal cells." (PMID 25333256, 2014). "To further elucidate the role of IFNβ1 in melanoma progression, we performed IHC on the same 91 human patient samples analyzed for TRIM16 expression." (PMID 25333256, 2014). "We first analyzed the TRIM16 protein expression level by Western blotting in 6 melanoma cell lines, and showed a significantly lower level, compared to a normal human epidermal melanocyte cell line (NHEM)." (PMID 25333256, 2014). "High levels of TRIM16 in melanoma tissues from patients treated with Vemurafenib correlated with clinical response." (PMID 25333256, 2014). "Our data, for the first time, demonstrates TRIM16 is a marker of cell migration and metastasis, and a novel treatment target in melanoma." (PMID 25333256, 2014). "TRIM16 protein levels were markedly reduced in human melanoma cell lines, compared with normal human epidermal melanocytes due to both DNA methylation and reduced protein stability." (PMID 25333256, 2014). "TRIM16 transcription also increased following 5-Aza treatment in melanoma cell lines (P=0.05), indicating direct or indirect de-repression of the TRIM16 gene transcription upon treatment with the demethylating agent." (PMID 25333256, 2014). "Knockdown of TRIM16 using TRIM16-specific siRNAs in the normal cellular counterpart of melanoma cells, NHEMs, resulted in a significant increase in cell migration (P<0.001)." (PMID 25333256, 2014). "Our data has for the first time demonstrated a novel action of vemurafenib in suppressing melanoma cell growth in a TRIM16-dependent manner." (PMID 25333256, 2014). "Low level TRIM16 expression in 91 melanoma patient samples, strongly correlated with lymph node metastasis, and, predicted poor patient prognosis in a separate cohort of 170 melanoma patients with lymph node metastasis." (PMID 25333256, 2014). "Some studies have also shown that TRIM16 can be used as a drug target in melanoma." (PMID 35230201, 2022). "Therefore, it is implied that WFA therapy, together with TRIM16 expression upregulation, can be a possible way of preventing disease development and serving as a support therapy for patients with stage II melanoma." (PMID 33919088, 2021). "Last, it is unknown whether TRIM16 reactivation by WFA potentiate another targeted anti-melanoma therapy." (PMID 33184347, 2020). "Moreover, suppression of TRIM16 expression increased migration of normal human epidermal melanocytes, while overexpression of TRIM16 reduced melanoma cell migration and proliferation." (PMID 33184347, 2020). "To evaluate whether induction of TRIM16 expression was essential for WFA to exert its effect on melanoma cell survival, we silenced TRIM16 gene expression using two TRIM16-specific siRNAs in MelJD and MelCV melanoma cells, followed by treatment with WFA." (PMID 33184347, 2020).
melanoma (continued). "We found that only heterozygous TRIM16+/flox knockout mice showed evidence of inguinal lymph node pigmentation which is concordant with the heterozygous TRIM16+/flox knockout mice, developing a greater number of melanoma skin lesions and SCCs." (PMID 31342168, 2019). "Furthermore, TRIM16 is lost during the progression of melanoma and correlates with human melanoma metastasis." (PMID 31342168, 2019). "This profile of TRIM27 function in cancer suggests that the activity of TRIM proteins can be pleiotropic and, hence, TRIM16 may suppress cell proliferation and migration in melanoma, but has the potential to increase tumorigenesis in SCC." (PMID 31342168, 2019). "IFN-γ also regulated TRIM16 gene expression and methylation in melanoma metastasis." (PMID 29467412, 2018). "It is unknown whether TRIM16 reactivation may potentiate other targeted anti-melanoma therapy and may have a wider application in enhancing drug treatments." (PMID 27447557, 2016). "Here, we implicate reactivation of TRIM16 as being partially required for tumor targeting by the combination therapy and suggest TRIM16 reactivation as an area for further investigation for melanoma treatment and a potential strategy for targeting BRAF wild-type and mutant melanomas." (PMID 27447557, 2016). "Moreover, we showed high levels of TRIM16 in melanoma tissues from patients treated with vemurafenib correlated with clinical response." (PMID 27447557, 2016). "As TRIM16 protein expression is known to induce apoptosis in neuroblastoma, we overexpressed TRIM16 in low TRIM16 expressing melanoma cell lines, Mel-JD, A753 and G361 and showed an increase in apoptosis in the TRIM16 overexpressing cells compared to empty vector controls (P < 0.05)." (PMID 27447557, 2016). "The proteasome inhibitor MG-132 increased TRIM16 protein levels in melanoma cells." (PMID 25333256, 2014). "The BRAF inhibitor, vemurafenib, suppressed melanoma cell growth in a TRIM16-dependent manner." (PMID 25333256, 2014). "We next examined the role of TRIM16 in melanoma cell migration." (PMID 25333256, 2014). "Low TRIM16 expression in localized melanoma tissue may identify a patient cohort who will benefit from systemic therapy aimed at increasing TRIM16 levels and preventing metastasis." (PMID 25333256, 2014). "This pattern was mirrored in melanoma tissue samples from patients treated with BRAF inhibitors, vemurafenib and dabrafenib, indicating that de-repression of TRIM16 expression in melanoma cells is a novel therapeutic approach and provides new insights into the mechanism of action of BRAF inhibitors." (PMID 25333256, 2014). "We confirmed by RT-qPCR that TRIM16 induced IFNβ1 and c-Jun mRNA expression in melanoma cells." (PMID 25333256, 2014). "Overexpression of TRIM16 reduced cell proliferation for all 5 melanoma cell lines." (PMID 25333256, 2014). "To determine whether loss of TRIM16 expression was also due to DNA methylation, we treated NHEM, WI38 and four melanoma cell lines with the demethylating agent, 5-aza-2′-deoxycytidine (5-Aza), at 30 μM for 72 hours." (PMID 25333256, 2014). "Therefore, we next determined the prognostic significance of low TRIM16 expression in an independent cohort of 170 melanoma patients with lymph node metastases (Stage III)." (PMID 25333256, 2014). "As exogenous overexpression of IFNβ1 reduces cell proliferation and induces apoptosis in melanoma cells, restoration of endogenous IFNβ1 signaling by TRIM16 may enhance the anticancer activities of exogenous IFNβ1." (PMID 25333256, 2014). "This study supports the thesis that keratinocyte-derived TRIM16 may inhibit melanoma metastasis." (PMID 33430277, 2021). "The mechanism by which TRIM16 expression is lost in melanoma cells is currently unknown." (PMID 33184347, 2020). "Therefore, we suggest that WFA treatment and upregulation of TRIM16 expression could be a potential method to prevent disease progression and serve as maintenance therapy for Stage II melanoma patients." (PMID 33184347, 2020).